RN7SKP145 (RN7SK pseudogene 145)
Gene: Miscellaneous RNA gene on chromosome 5 (149,116,178 to 149,116,480, reverse strand). Ensembl gene ENSG00000200161.
Homologues: Orthologues: chimpanzee 7SK (88% identical). Paralogues in human: RN7SKP255 (77% identical), RN7SKP71 (75% identical), RN7SKP237 (74% identical), RN7SKP149 (74% identical), RN7SKP75 (74% identical), RN7SKP224 (73% identical), RN7SKP79 (73% identical), RN7SKP189 (73% identical), RN7SKP78 (73% identical), RN7SKP90 (73% identical), 7SK (73% identical), RN7SKP163 (73% identical), and 284 more.